CGAS (cyclic GMP-AMP synthase)
Diseases named in the same sentence as CGAS in open-access papers (continued):
Sharing a sentence is not in itself a finding about the gene and the disease.
liver diseases (17 papers, 2021 to 2025). "Functionally, cGas‐/‐ mice fed with a modified high‐fat diet develop exacerbated metabolic dysfunction‐associated steatotic liver disease (MASLD), characterized by excessive lipid droplet accumulation in livers compared to wild‐type controls." (PMID 41042077, 2025). "Accumulating evidence has implicated the important role of the cGAS-STING signaling pathway in the pathogenesis of multiple liver diseases." (PMID 34483930, 2021). "In conclusion, the cGAS-STING signaling pathway is closely associated with liver disease progression and represents a significant potential direction for therapeutic research." (PMID 34483930, 2021). "Altogether, cGAS associated autophagic processes play a critical role in liver diseases, which may furnish fresh thought to the treatment for liver disease." (PMID 34483930, 2021). "Other liver diseases have also been shown to be associated with the cGAS-STING pathway." (PMID 34386500, 2021). "Understanding and precisely modulating the activation thresholds and signal outputs of cGAS-STING across different hepatic cells enables intervention in liver disease progression at molecular, cellular, and tissue levels." (PMID 41438738, 2025). "Our group is dedicated to investigating the regulation of the cGAS‐STING pathway and its association with liver diseases." (PMID 39877286, 2025). "The cGAS-STING pathway has recently attracted significant attention in liver disease research due to its crucial role in regulating immune responses." (PMID 41438738, 2025). "The discovery of the role of cGAS-STING pathway in liver disease offers exciting new avenues for therapeutic intervention, potentially leading to novel treatments." (PMID 40098962, 2025). "Accumulating evidence has highlighted the significance of the cGAS-STING pathway in diverse hepatic disorders, including NAFLD, ALD, viral hepatitis, HIRI, C-DILI, Liver Neoplasms, Liver Cirrhosis, and Parasitic Liver Disease." (PMID 41438738, 2025). "This review highlights the complex role of cGAS-STING signaling in these specific liver diseases and underscores the need for further research to fully realize its therapeutic potential." (PMID 40098962, 2025). "Building on these insights, our review provides a comprehensive synthesis of the literature linking the cGAS–STING pathway to a broad spectrum of liver diseases." (PMID 41438738, 2025). "Although the cGAS-STING axis plays a critical role in the pathogenesis of numerous hepatic diseases, further clinical investigation is warranted to assess its therapeutic potential." (PMID 40098962, 2025). "Studies on the role of cGAS-STING in inflammatory liver diseases with inadequate or unfulfilled treatment options suggest its potential as a target for therapeutic development." (PMID 39183465, 2024). "In this article, we summarize the impact of cGAS-STING signalling on various liver inflammatory diseases and evaluate its potential as a therapeutic target for liver inflammation." (PMID 39183465, 2024). "In this study, we reviewed the regulatory mechanisms and biological functions of the cGAS-STING pathway through its involvement in aseptic inflammation in liver disease, kidney disease, and cellular senescence." (PMID 39114669, 2024). "Emerging evidence has shown that cGAS-STING signaling plays a critical role in liver diseases, including IR injury." (PMID 36765043, 2023). "Recent studies have shown that the cGAS-STING pathway plays an important role in various liver diseases." (PMID 36765043, 2023). "cGAS is a newly discovered DNA sensor, which is considered to involve in the development of diverse liver diseases, such as viral hepatitis, NAFLD, drug-induced liver injury (DILI), and HCC." (PMID 37020586, 2023). "Thereby, the agonist of the cGAS-STING signaling pathway can be used in liver disease treatment, providing a new idea for understanding and treating liver diseases." (PMID 35252042, 2022).
liver diseases (continued). "Although the cGAS-STING pathway has been previously considered to have essential roles in innate immunity and host defense, recent advances have extended the role of the cGAS-STING pathway to liver diseases." (PMID 33995425, 2021). "Understanding the structural features and functions of cGAS-STING will provide new insights for the treatment of liver diseases based on this pathway through novel methods and agents." (PMID 34386500, 2021). "This molecular regulatory network permeates multiple cell types and traverses multilayered pathological processes, positioning cGAS-STING as a pivotal signaling hub in hepatic disorders, intimately connecting upstream DNA pattern recognition with downstream histopathological alterations." (PMID 41438738, 2025). "Altogether these studies verify effects of cGAS-STING pathway on apoptosis in liver diseases." (PMID 39183465, 2024). "cGAS-STING signalling is vital to pyroptosis in various liver diseases." (PMID 39183465, 2024). "Accumulating evidence indicates that ferroptosis influences cGAS-STING signalling in liver diseases, suggesting that oxidative stress-induced ferroptosis and macrophage-associated inflammation are important factors in several liver disorders." (PMID 39183465, 2024). "Therefore, inhibitors of the cGAS-STING pathway are prospective targets for the treatment of inflammatory liver diseases." (PMID 39183465, 2024). "The cGAS-STING pathway promotes apoptosis in various liver diseases." (PMID 39183465, 2024). "Increasing evidence indicates that the overactivation of TLRs and the cGAS signaling pathways may contribute to the development of liver disorders, including NAFLD progression." (PMID 37020586, 2023). "Emerging evidence indicates that overactivation of cGAS-STING may contribute to the development of liver disorders, implying that the cGAS-STING pathway is a promising therapeutic target." (PMID 33995425, 2021). "Additionally, we discuss various pharmacological agonists and antagonists of cGAS-STING signaling as novel therapeutics for the treatment of liver diseases." (PMID 34386500, 2021). "Role of cGAS–STING signaling pathway in liver disease and relevant therapeutic target." (PMID 34483930, 2021). "In addition to HBV and liver cancer, the cGAS–STING pathway has been shown to be activated in other kinds of liver diseases (e.g., non-alcoholic fatty liver disease (NAFLD), alcohol liver disease (ALD), liver ischemia–reperfusion, etc.)." (PMID 34906241, 2021). "Therefore, this review summarized the regulatory functions and mechanisms of the cGAS–STING signaling pathway in various liver diseases." (PMID 34483930, 2021). "Moreover, we summarize and discuss the role of the cGAS-STING DNA pathway in a variety of liver diseases." (PMID 33995425, 2021). "In conclusion, the cGAS-STING signaling pathway represents a highly promising direction of research in the field of liver diseases, especially viral liver infections and cancer therapy, both at the genetic and protein levels, which shed new light on the treatment of liver disease." (PMID 34483930, 2021). "Understanding these context-dependent functions of cGAS-STING pathway provides critical insights for the development of targeted therapeutic strategies that may selectively modulate this pathway to treat diverse hepatic disorders." (PMID 41438738, 2025). "In addition to several common liver diseases summarized above, the current studies suggest that the cGAS-STING signaling pathway may also involve autoimmune liver diseases." (PMID 34483930, 2021). "The cGAS-STING pathway, an innate immune defense pathway that functions via the recognition of dsDNA by cGAS and leads to the transcription of interferons by STING, is known to be heavily involved in HCC and other liver diseases." (PMID 40500404, 2025). "Emerging research indicates that cGAS-STING signaling is intricately involved in maintaining liver homeostasis and contributes to the pathogenesis of various liver diseases." (PMID 40098962, 2025).
liver diseases (continued). "More and more studies have revealed that the cGAS-STING pathway is involved in the pathogenesis and progression of several liver diseases." (PMID 40621423, 2025). "This article presents an in-depth exploration of the cGAS-STING pathway, with a particular emphasis on its activation process and its multifaceted implications for liver disease." (PMID 40098962, 2025). "Ultimately, the cGAS-STING pathway embodies both a beacon of hope and a cautionary tale in liver disease therapeutics." (PMID 40098962, 2025). "In this review, we emphasize the reaction of the cGAS-STING signaling mechanism to self-abnormal DNA and describe the current developments in kidney disease, liver disease, and cellular senescence." (PMID 39114669, 2024). "The potential connection between cGAS-STING pathway and liver inflammatory diseases has recently been reported widely." (PMID 39183465, 2024). "The potential impact of cGAS-STING pathway in hepatic ischemia reperfusion (I/R) injury, alcoholic/non-alcoholic steatohepatitis (ASH), hepatic B virus infection, and other liver diseases has recently attracted widespread attention." (PMID 34386500, 2021). "The development of drugs that inhibit or promote the cGAS-STING signaling pathway has broad prospects for treating HCC, ALD, NASH, HBV, and other liver diseases, giving it a major role in basic immunology, tumor biology, and clinical treatment." (PMID 34386500, 2021). "Recent studies have found that the cGAS-STING signaling pathway played a significant role in liver physiology and was closely related to the progress of liver diseases." (PMID 34483930, 2021). "In this review, the relationship between cGAS-STING pathway and the pathophysiological mechanisms and progression of liver diseases is summarized." (PMID 34386500, 2021). "Recently, researchers found that the cGAS–STING signaling pathway was closely related to the occurrence and development of multiple liver diseases." (PMID 34483930, 2021). "In this review, we discuss cGAS-STING signaling in liver diseases, and the profound implications of this pathway for novel therapeutic approaches against liver diseases." (PMID 34386500, 2021). "The role of the cGAS-STING pathway axis in liver disease is not unidimensional; rather, it exhibits a classic “double-edged sword” effect." (PMID 41438738, 2025). "CGAS-STING signaling pathway activation has a remarkable inhibitory effect on liver viral infection and cancer, thus becoming an exciting target in the field of liver disease immunology and oncology in recent years." (PMID 34483930, 2021).
lung adenocarcinoma (17 papers, 2021 to 2025). A carcinoma that arises from the lung and is characterized by the presence of malignant glandular epithelial cells. "Recent evidence showed that DNA damage and accumulation of cytosolic dsDNA leads to activation of the cGAS-dependent STING pathway in lung adenocarcinoma cells." (PMID 38672164, 2024). "And cGAS can regulate SASP by activating NF‐κB,46, 47 knocking down cGAS abolished the SASP phenotype, and the prognosis of lung adenocarcinoma patients with low cGAS expression was poor." (PMID 39161800, 2024). "For example, analyses of TCGA datasets indicate that >30% of high expressing STING lung adenocarcinoma or testicular cancer tumors have low cGAS expression." (PMID 35087822, 2021). "Based on our finding that STAT2 preferentially inhibits the induction of IRF3-dependent genes, we propose that the IKKi-induced T404 phosphorylation of STAT2 mediates tumor progression in lung adenocarcinoma by inhibiting the tumor-suppressive function of the cGAS–STING pathway." (PMID 37036972, 2023). "In lung adenocarcinoma, silencing RRM2 expression exerted anti-tumor effects by activating the cGAS/STING signaling pathway." (PMID 37056349, 2023). "The role of APE1 in modulating the cGAS-STING pathway may be tissue-specific, considering recent findings showing that in lung adenocarcinoma, APE1 contributes to radiation resistance by inhibiting this pathway." (PMID 41463362, 2025).
pulmonary fibrosis (17 papers, 2020 to 2026). Chronic progressive interstitial lung disorder characterized by the replacement of the lung tissue by connective tissue, leading to progressive dyspnea, respiratory failure, or right heart failure. "In pulmonary fibrosis, leakage of damaged mtDNA or self-DNA into the cytoplasm activates cytoplasmic cGAS, causing an inflammatory response that triggers cellular senescence." (PMID 37965345, 2023). "Nasal instillation of PS nanoplastics in mice has been shown to induce pulmonary fibrosis through mitochondrial DNA release and subsequent cGAS-STING pathway activation, aggravating lung inflammation." (PMID 40508037, 2025). "In summary, we reported a new finding that heat exposure contributed to the development of early pulmonary fibrosis-like changes through the DNA damage-activated cGAS–STING pathway followed by cellular senescence." (PMID 38474239, 2024). "Mitochondrial dysfunction, mtDNA release, and activation of cGAS/STING signaling are known pathomechanistic features of pulmonary fibrosis." (PMID 36912165, 2023). "Our data thus link induction of the immunoproteasome by DNA stress to cell‐intrinsic and chronic activation of autoreactive CD8+ T cells via the cGAS/STING pathway suggesting a novel pathomechanism for pulmonary fibrosis." (PMID 36912165, 2023). "Recent studies have highlighted the involvement of aberrant activation of cGAS-STING contributes to fibrotic lung diseases, such as sting-associated vasculopathy of infantile onset (SAVI), IPF, and silica-induced lung fibrosis." (PMID 37965345, 2023). "Conversely, blockage of cGAS-STING signaling pathway to suppress inflammatory response is an important aspect of lung fibrosis treatment." (PMID 37965345, 2023). "This review aims to provide a comprehensive summary of the current knowledge regarding the role of cGAS-STING pathway in pulmonary fibrosis." (PMID 37965345, 2023). "In patients with idiopathic pulmonary fibrosis, chronic activation of the cGAS/STING‐induced adaptive immune response in aberrant lung epithelial cells concurs with CD8+ T‐cell activation in diseased lungs." (PMID 36912165, 2023). "The inflammatory response induced by activation of the cGAS-STING signaling pathway is a significant factor in the progression of pulmonary fibrosis." (PMID 37965345, 2023). "Nevertheless, persistent enhanced airway dsDNA in the BALF associated with a strong increase of lung cGAS and STING expressions at the fibrotic stage led us to investigate a role for this pathway in the establishment of pulmonary fibrosis." (PMID 33488589, 2020). "Moreover, treatments such as Tanreqing (TRQ) and fluvoxamine effectively inhibit the release of inflammatory factors and reduce the level of pulmonary fibrosis by targeting the cGAS-STING signaling pathway." (PMID 39540037, 2024). "By injecting bleomycin (BLM) into the trachea to create a mouse model of pulmonary fibrosis, researchers discovered that activation of the cGAS-STING signaling pathway promotes the expression of inflammatory factors and accelerates the aging of lung fibroblasts." (PMID 39540037, 2024). "Therefore, in this study, we investigated the pathological process of pulmonary fibrosis in heat-exposed mice and tried to explain the mechanism from the perspective of DNA damage/the cGAS–STING signaling pathway/the cellular senescence axis." (PMID 38474239, 2024). "In bleomycin-induced pulmonary fibrosis, activation of the cGAS-STING signaling pathway not only leads to the production of numerous SASP factors such as IL-6, IL-8, and the upregulation of cell cycle-related factors p16 and p21, but also increased secretion of inflammatory factors like IFN-β." (PMID 37965345, 2023). "Additionally, the induction of cellular senescence through damaged autologous DNA-mediated cGAS activation contributes to lung fibrosis, while targeting the cGAS-STING pathway can bypass cellular senescence and attenuate the fibrotic process." (PMID 37965345, 2023).
pulmonary fibrosis (continued). "Targeting cGAS-STING signaling has shown potential in alleviating pulmonary fibrosis." (PMID 37965345, 2023). "The DNA‐sensing cGAS/STING pathway regulates immunoproteasome function and MHC class I antigen presentation to promote T‐cell activation that may underlie pathology of idiopathic pulmonary fibrosis." (PMID 36912165, 2023). "The present review offers a comprehensive summary of the current knowledge on the involvement of the cGAS-STING pathway in pulmonary fibrosis, as well as an exploration of cGAS and STING agonists and inhibitors, with a focus on their therapeutic potential for treating pulmonary fibrosis." (PMID 37965345, 2023). "Hence, the activation of the cGAS-TING pathway in macrophages is probably related to lung fibrosis and the inflammatory response of RP mice." (PMID 35892659, 2022). "In addition to its involvement in COPD, cGAS–STING also plays a significant role in pulmonary fibrosis." (PMID 34906241, 2021). "The different expression levels of STING in silica-induced and idiopathic pulmonary fibrosis show that there may be different cGAS–STING regulatory mechanisms for different etiological conditions." (PMID 34906241, 2021). "Recent studies have shown that cGAS-STING primarily participates in the development and progression of pulmonary fibrosis by responding to both exogenous and endogenous DNA." (PMID 37965345, 2023). "Cytoplasmic DNA sensing through the cGAS/STING pathway serves as an activator for the immunoproteasome and CD8+ T cells, uncovering a new potential pathological mechanism for pulmonary fibrosis." (PMID 37354378, 2023). "In addition, PS-MPs promote cellular ferroptosis and activate the cyclic GMP-AMP synthase (cGAS)/stimulator of interferon genes (STING) signaling pathway, thereby contributing to the progression of pulmonary fibrosis." (PMID 40141737, 2025). "Therefore, further exploration of the correlation between the cGAS-STING signaling pathway and pulmonary fibrosis is crucial for developing novel therapeutic methods." (PMID 39540037, 2024). "Moreover, we provide evidence for an activation of this pathway, which we term cGAS/STING‐induced adaptive immune response, in aberrant epithelial cells from patients with idiopathic pulmonary fibrosis (IPF)." (PMID 36912165, 2023). "Since cGAS-STING pathway plays important roles in pulmonary fibrosis, these studies further suggest that inhibition of this pathway attenuates cellular senescence and further alleviates pulmonary fibrosis." (PMID 37965345, 2023). "In mice with graphitized multi-walled carbon nanotube (GMWCNT)-induced pulmonary fibrosis, high expression of cGAS, STING, IFN-β, NF-κB, IL-1β, and TGF-β1 indicates the induction of an inflammatory response through activation of the cGAS-STING signaling pathway." (PMID 37965345, 2023). "In summary, we first identified that DNA damage occurred in the lungs of mice under heat exposure, which may subsequently lead to the activation of the cGAS–STING signaling pathway, contributing to lung tissue senescence and, ultimately, early pulmonary fibrosis-like changes." (PMID 38474239, 2024). "cGAS/STING signaling is also activated by dysfunctional telomeres that might link telomere dysfunction as found in sporadic and hereditary IPF to development of pulmonary fibrosis." (PMID 36912165, 2023). "Previous studies have demonstrated that mtDNA can trigger inflammatory cytokine production and aggravate lung fibrosis through TLR9 signaling and noncanonical cGAS-STING signaling." (PMID 38790051, 2024).